MIR4317 (microRNA 4317)
Synonyms: hsa-mir-4317
Gene: MicroRNA gene on chromosome 18 (6,374,361 to 6,374,425, reverse strand). Ensembl gene ENSG00000283532.
Homologues: Orthologues: macaque MIR4317 (100% identical).